UQCRBP1 (ubiquinol-cytochrome c reductase binding protein pseudogene 1)
Gene: Transcribed processed pseudogene on chromosome X (56,737,242 to 56,737,577, reverse strand). Ensembl gene ENSG00000237748.
Diseases named in the same sentence as UQCRBP1 in open-access papers:
UQCRBP1 is named in the same sentence as 1 disease in open-access papers, as found by Europe PMC text mining. Sharing a sentence is not in itself a finding about the gene and the disease. The quoted sentences say what the papers report.
cancer (1 paper, 2025). A tumor composed of atypical neoplastic, often pleomorphic cells that invade other tissues. "UQCRBP1, positively co‐expressed with SFXN4, is also likely upregulated in HCC, suggesting a shared role in cancer progression." (PMID 40556338, 2025).